MYB (MYB proto-oncogene, transcription factor)
Diseases named in the same sentence as MYB in open-access papers (continued):
Sharing a sentence is not in itself a finding about the gene and the disease.
acute myeloid leukemia (60 papers, 2011 to 2026). Acute myeloid leukemia (AML) is a group of neoplasms arising from precursor cells committed to the myeloid cell-line differentiation. "MYB genes contain an N-terminal DNA-binding domain (DBD), a C-terminal negative regulatory domain (NRD) and a central trans-activation domain (TAD); v-myb is derived from mutations in the MYB gene and can cause severe acute myeloid leukemia in vertebrates." (PMID 36386181, 2022). "Previous research in acute myelogenous leukemia cells have shown that BET proteins control the association of MED subunits with the MYB oncogene." (PMID 34765643, 2021). "Recent work has highlighted the role of transcription factor MYB in acute myeloid leukemia (AML) and has suggested MYB as a potential drug target for AML and other malignancies associated with deregulated MYB function." (PMID 35406726, 2022). "Their study revealed that loss of TAF12 function could impair MYB activity and cause regression of acute myeloid leukemia (AML) in a mouse model." (PMID 36551275, 2022). "MYB is known to suppress apoptosis in acute myeloid leukemia cells by transcriptional repression of DRAK2 alias STK17B." (PMID 34294125, 2021). "Recent work has suggested that targeting MYB by small-molecule inhibitors is feasible and that inhibition of MYB has potential as a therapeutic approach against acute myeloid leukemia." (PMID 30177851, 2018). "MYB activity is a key factor for the maintenance of acute myeloid leukemias but it is also a difficult target." (PMID 29317678, 2018). "We previously showed that MYB was a direct activator of FLT3 expression within the context of acute myeloid leukaemia." (PMID 26382271, 2015). "The identification of specific, essential and druggable transcriptional regulators may enable effective targeting of MYB expression, which in turn could potentially lead to new therapeutic approaches for acute myeloid leukaemia with MLL-AF9." (PMID 31882723, 2019). "Studies on the role of transcription factor MYB in acute myeloid leukemia (AML) have identified MYB as a key regulator of a transcriptional program for self-renewal of AML cells." (PMID 36913305, 2023). "In this work, we show that combinatorial treatment of acute myeloid leukemia (AML) cells with DNA methylation inhibitors (5-Azacytidine), MYB inhibitors (Celastrol), and anti-miR-155 (AM155) ideally leads to overproduction of PU." (PMID 35743167, 2022). "Here, we show that most subtypes of acute myeloid leukemia (AML) depend on the aberrant assembly of MYB transcriptional co-activator complex." (PMID 33527899, 2021). "In acute myeloid leukemia (AML), MYB rearrangements are rare; however, AML cells are often addicted to high levels of MYB, making them more vulnerable to MYB inhibition than their normal counterparts." (PMID 35008207, 2021). "Transcription factor MYB has recently emerged as a promising drug target for the treatment of acute myeloid leukemia (AML)." (PMID 33958723, 2021). "For instance, the METTL3 and METTL14, highly expressed in acute myeloid leukemia (AML), play a critical role in leukemia progression through promoting translation of target mRNAs, including MYB, MYC, BCL2, and PTEN." (PMID 33292652, 2020). "The transcription factor c-MYB plays a central role in the development of acute myeloid leukemia (AML) and other tumors." (PMID 31480477, 2019). "Other studies have reported the overexpression of MYB, DNMT3B, and MYCN in acute myeloid leukaemia patients." (PMID 40911615, 2025). "MYB is an oncogene that is widely expressed in acute myeloid leukemia (AML)." (PMID 40234694, 2025). "For instance, in acute myeloid leukemia (AML), increased m6 A levels on SP1, MYB, MYC, BCL2, and PTEN enhance the stability and translation of their corresponding mRNAs, contributing to the onset and progression of AML." (PMID 40382536, 2025).
acute myeloid leukemia (continued). "DRAK2 plays an important role in v-myb-mediated acute myeloid leukemia, and CHIP indicates that MYB binds to a conserved element upstream of the DRAK2 transcription start site." (PMID 36386181, 2022). "It was reported that METTL14 overexpression in acute myeloid leukemia is negatively regulated by SPI1 and mediates downstream targets, MYB and MYC, to accelerate acute myeloid leukemia (AML) oncogenesis." (PMID 34904301, 2022). "Moreover, in acute myeloid leukemia (AML), MYB expression activates miR-155 and inhibits transcription factor PU." (PMID 34876130, 2021). "In addition, Acute Myeloid Leukemia (AML) cells are “addicted” to high expression levels of MYB, making them more vulnerable to inhibition of MYB than normal HPCs." (PMID 33958723, 2021). "Through its tAD, MYB interacts with the KIX-domain of the histone acetyl transferases p300 and CBP17–21, an interaction which is required for the induction of acute myeloid leukemia (AML) and appears to be a promising therapeutic target for AML treatment." (PMID 33903675, 2021). "METTL14 was shown to exert its oncogenic role by regulating MYB and MYC through m6A modification in acute myeloid leukemia (AML), whereas it also suppressed tumorigenesis and metastasis of bladder cancer or hepatocellular carcinoma (HCC)." (PMID 34149792, 2021). "Suppression of MYB mRNA by miR-107 revealed a possible mechanism of acute myeloid leukemia (AML) resistance to the antileukemic nucleoside cytarabine in AML cell lines and patient samples, which indicates a tumor suppressor role of MYB in the interplay with miR-107." (PMID 38835346, 2024). "MYB protein levels were previously shown to be strongly induced upon SOX11 overexpression (SOX11 OE), while celastrol has been reported to inhibit MYB activity in cancer cells (acute myeloid leukemia)." (PMID 38181013, 2024). "To first investigate this in a cellular context independent of the pDC lineage and using endogenous MYB expression levels, we knocked in V5-tagged MYB constructs to the endogenous MYB locus of the acute myeloid leukemia (AML) cell line K562." (PMID 39499902, 2024). "Indeed, Acute Myeloid Leukemia (AML)-derived EVs enriched in miR-150 and miR-155 impaired hematopoietic stem and progenitor cell (HSPC) clonogenicity through suppression of c-MYB translation." (PMID 31137912, 2019). "Unlike T-ALL, direct genomic rearrangements affecting MYB in acute myeloid leukemia (AML) are rare." (PMID 38542205, 2024). "Similarly, in acute myeloid leukemia, BRD4 has been shown to co-localize and synergistically interact with hematopoietic TFs (including PU.1, FLI1, ERG, C/EBPα, C/EBPβ, and MYB) combined with lysine acetyltransferase p300/CBP to support specific transcriptional circuits in this disease." (PMID 37446009, 2023). "In acute myeloid leukemia (AML), METTL14 regulates MYB and MYC via M6A modification, and plays a carcinogenic role in regulating cell self-renewal and inhibiting bone marrow differentiation." (PMID 35552266, 2022). "It was found that METTL3 and METTL14 (writers) served an oncogenic role in acute myeloid leukemia (AML) in an m6A manner by promoting the translation of MYC, MYB, BCL2, SP1, and PTEN." (PMID 36281789, 2022). "METTL14 regulates mRNA stability and the translation of MYB and MYC genes, players in the self-renewal and differentiation of normal HSCs and acute myeloid leukemia (AML) cells." (PMID 32916783, 2020). "ARQ 531 could target multiple pathways including BTK, MYB, AKT, ERK, and other pathways in acute myeloid leukemia (AML)." (PMID 33676527, 2021). "Importantly, although MYB rearrangements are not detected in the majority of acute myeloid leukemia (AML) cells, these cells are more vulnerable to MYB inhibition than their normal counterparts indicating that they are addicted to high levels of MYB activity." (PMID 30177851, 2018).
glioma (56 papers, 2008 to 2025). A benign or malignant brain and spinal cord tumor that arises from glial cells (astrocytes, oligodendrocytes, ependymal cells). "High MYB expression is associated with the malignant progression of pancreatic cancer, glioma, and cervical cancer." (PMID 40888643, 2025). "In glioma patients with MYB and MYBL1 mutations, the clinical course is generally indolent." (PMID 34638714, 2021). "Among CNS tumors, MYB or MYBL1 alterations are noted in the current World Health Organization (WHO) classification as 2 tumor types: “Angiocentric glioma” and “Diffuse astrocytoma, MYB- or MYBL1-altered,” both as WHO grade 1." (PMID 39422766, 2024). "Diffuse gliomas with MYB/MYBL1 rearrangement were mainly presented in children, and most of the patients had epileptic seizures together with neurological symptoms such as movement disorders, behavioral or memory changes." (PMID 38315329, 2024). "Angiocentric glioma and diffuse astrocytoma MYB/MYBL1 altered tumors show overlapping histopathological features and both express MYB gene involvement." (PMID 39440342, 2024). "Almost all angiocentric gliomas have MYB alterations, with the most frequent rearrangement being represented by MYB::QKI fusion." (PMID 38544524, 2024). "MYB/MYBL1 altered diffuse glioma and angiocentric glioma show overlapping microscopic morphology and are characterized by MYB gene involvement." (PMID 39440342, 2024). "Case 2 clustered closely to the MC ganglioglioma, and Case 3 exhibited an independent methylation signature near the reference methylation group for low-grade glioma, MYB-altered." (PMID 38926750, 2024). "In analogy to the discovery of MYB/NFIB fusions in ACC cells, recent work has also uncovered recurrent translocations of MYB or MYBL1 with several other genes in pediatric low-grade gliomas." (PMID 38542205, 2024). "Study cases included those which matched to the “Diffuse glioma, MYB- or MYBL1-altered” family by the CNS methylation classifier." (PMID 39422766, 2024). "Angiocentric gliomas typically show alterations in the MYB gene, most often rearrangements with QKI as a partner, although other partners have been also described." (PMID 39422766, 2024). "The MYB-QKI fusion in GBM mainly occurs in angiogenic gliomas, primarily affecting the stemness of glioblastomas." (PMID 39479357, 2024). "A final diagnosis of angiocentric glioma was reached in 6 cases, and the remaining 8 cases were diagnosed as diffuse astrocytoma, MYB- or MYBL1-altered." (PMID 39422766, 2024). "Taken together, the histopathological classification, molecular-genetic and epigenetic features, clinical behavior, and pontine location have led us to reclassify the tumor as a pontine MYB-altered glioma." (PMID 37165121, 2023). "Research showed different molecular markers in tumors between children and adults, with pediatric low-grade gliomas predominantly exhibiting alterations in the BRAF, FGFR, and MYB/MYBL1 genes, while IDH1/2 mutations were less common." (PMID 38137148, 2023). "Genome-wide DNA methylation array was performed, and the sample was classified using the v12.5 version of the Heidelberg classifier into the methylation class “Low-grade glioma, MYB(L1) altered” with a calibrated score of 0.90." (PMID 37165121, 2023). "Among those, the most common combinations (21/24) included anaplastic (pilocytic) astrocytomas or glioblastomas (WHO grade 3–4) assigned to DNA methylation classes of lower-grade gliomas, including PA, GG or MYB/MYBL-altered tumors (WHO grade 1–2)." (PMID 36928815, 2023). "Translocations fusing MYB with different other loci occur frequently in low-grade pediatric gliomas." (PMID 35408476, 2022). "This is particularly important to recognize in the AYA population, where gliomas with alterations in the MAPK pathway or MYB and MYBL1 have distinctly different prognoses from other glioma subtypes and offer possibilities for targeted therapy." (PMID 36249063, 2022).
glioma (continued). "Other fusion partners of MYB in pediatric gliomas have also been identified: ESR1, MAML2, MMP16 and PCDHGA1 (Online Resource 17)." (PMID 35169893, 2022). "To validate our prediction, we established two Flag-tagged, MYB overexpression glioma cell lines (SW1088 and LN229) and performed Chromatin immunoprecipitation." (PMID 34868977, 2021). "In the IDH-wildtype glioma group (i.e., glioblastoma, low-grade glioma MYB/MYBL1 and (anaplastic) pleomorphic xanthoastrocytoma), MGMT promotor was methylated in 29% (5/17) and unmethylated in 71% (12/17) of the cases." (PMID 33941250, 2021). "In gliomas, MYB gene alterations are detected more frequently in young children and typically affect the cerebral hemispheres." (PMID 34638714, 2021). "MYB fusions have been reported as rare events in pediatric low-grade gliomas, and first described in a total of 9 tumors of which two were angiocentric gliomas." (PMID 32151273, 2020). "To validate our assumption, we firstly detected the expression of ASAP3 and MYB in glioma cells treated with altered expression levels of miR-590-3p and ZNF143 expression." (PMID 31186064, 2019). "Our results suggested that overexpression of miR-590-3p obviously reduced the expression of ASAP3 and MYB, thereby restraining the biological behaviors of glioma cells." (PMID 31186064, 2019). "MYB has been proven to be highly expressed in glioma cells and promotes cell proliferation, migration and invasion." (PMID 31186064, 2019). "In our further studies, the ASAP3 and MYB expression of glioma cells treated with altering miR-590-3p and ZNF143 expression levels was detected." (PMID 31186064, 2019). "A recent study reported the identification of a specific abnormality in seven angiocentric gliomas: in fact, all these tumors harbored MYB translocations, mostly represented by MYB-QKI fusions and, more rarely, by MYB-ESR1 fusion." (PMID 30279357, 2018). "This includes a case of angiomatoid fibrous histiocytoma with EWSR1-CREM fusion, an angiocentric glioma with MYB-QKI fusion, a glioma with MYCN amplification, two patients with non-canonical IDH mutations (both with IDH1 R132S), and a patient with a KRAS mutation." (PMID 38764578, 2024). "However, almost all angiocentric glioma show MYB rearrangements and, most frequently, a MYB::QKI fusion." (PMID 38544524, 2024). "For example, adult gliomas are often driven by IDH1 or IDH2 mutations, while subsets of low-grade pediatric gliomas are driven by rearrangements in the transcription factor-encoding proto-oncogenes MYB or MYB like 1 (MYBL1)." (PMID 38353122, 2024). "There are few studies on the radiologic characteristics of MYB/MYBL1-altered gliomas." (PMID 38137148, 2023). "The tumor belongs to the family of MYB/MYBL1-altered gliomas and is an IDH-wild type." (PMID 37920791, 2023). "This group consists of 4 types of tumors: Diffuse astrocytoma, MYB- or MYB-Like 1 (MYB-L1)-altered, Angiocentric glioma, Polymorphous low-grade neuroepithelial tumor of the young and Diffuse low-grade glioma, Mitogen-Activated Protein Kinase (MAPK) pathway-altered." (PMID 36154607, 2023). "Interestingly, when DNA methylation data were analyzed using T-distributed Stochastic Neighborhood Embedding (tSNE) analysis, the tumor clustered between K27M and MYB low grade glioma clusters." (PMID 35484611, 2022). "Interestingly, DNA methylation analysis demonstrated that the tumor clustered with H3 K27M gliomas and MYB low grade gliomas." (PMID 35484611, 2022). "Although structural variants involving MYB have been described to be associated with angiocentric glioma, an extensive histopathological review of the MYB tumour did not detect any angiocentricity." (PMID 35836307, 2022). "The significance of QKI deregulation in brain tumors is further highlighted by the observation that 90% of angiocentric gliomas, a type of low-grade pediatric glioma, contain MYB-QKI fusions, which transform cells by concomitantly activating MYB and suppressing QKI." (PMID 35653194, 2022).
glioma (continued). "Similarly, translocations fusing MYB with various other loci occur frequently in low-grade pediatric gliomas." (PMID 35008207, 2021). "We observed the elevated SMC4 in the MYB overexpressed glioma cells." (PMID 34868977, 2021). "Therefore, WHO CNS5 introduced a new type of glioma called diffuse astrocytoma, MYB- or MYBL1-altered belonging to the family of pediatric-type diffuse low-grade gliomas." (PMID 34638714, 2021). "In gliomas, melatonin may affect the expression of MYB to inhibit miR-155, thus inhibiting the proliferation, migration and invasion of glioma cells." (PMID 34876130, 2021). "Lastly, MYB gene is altered in nearly all Angiocentric gliomas." (PMID 34638714, 2021). "Overall, these findings indicated that miR-590-3p could impede ASAP3 and MYB expression by downregulating ZNF143 in glioma cells." (PMID 31186064, 2019). "Therefore, ASAP3 and MYB are involved in mediating the regulatory effects of miR-590-3p on glioma cell progression, after being activated by ZNF143." (PMID 31186064, 2019). "However, local MYB expression was detected in several other low-grade gliomas." (PMID 39098857, 2025). "MYB alterations are in common with diffuse astrocytoma, MYB- or MYBL1-altered, which represents the closer differential diagnosis and, in rare cases, may also harbor the hallmark fusion of angiocentric glioma." (PMID 38544524, 2024). "cMYC inhibitor may hold promise for the management of tumors caused by MYB and MYBL1 translocations, Downstream MEK inhibitors are already in phase 2 in clinical trials for children with BRAF fused gliomas and phase 1 studies with FGFR1 inhibitors have started recently." (PMID 35574540, 2022). "Therefore, correlation between melatonin and MYB/miR-155 may provide a new strategy for the treatment of human gliomas." (PMID 34876130, 2021). "We speculate that there may be a close relationship between miR-148a and MYB in gliomas." (PMID 34876130, 2021). "It has been suggested that melatonin may be a therapeutic strategy for MYB-miRNA-induced glioma." (PMID 34876130, 2021). "Low-grade gliomas with duplication of FGFR1 TKD or MYB overexpression show activation of the MAPK/ERK and PI3K pathways, showing expression profiles similar to those of pilocytic astrocytomas with BRAF fusions and suggest that these pathways may represent potentially important therapeutic targets." (PMID 30279357, 2018). "Diffuse astrocytoma, MYB- or MYBL1-altered, CNS WHO grade 1, is a newly recognized tumor entity in the 2021 World Health Organization classification of central nervous system tumors." (PMID 40861626, 2025). "In conclusion, our study elucidates the diverse set of rearrangements that occur in the MYB and MYBL1 genes in MYB(L1)-altered glial neoplasms." (PMID 39422766, 2024). "Diffuse astrocytoma, MYB/MYBL1 altered, and angiocentric glioma are classified as WHO grade 1 tumors." (PMID 39440342, 2024). "Angiocentric glioma was included in the previous WHO CNS 4 and is now recognized to have a characteristic MYB::QKI gene fusion in nearly all cases." (PMID 36617415, 2023). "DNA methylation data of pediatric gliomas with a MYB or MYBL alteration cluster together as one entity, which is now classified as a new subtype of diffuse gliomas: diffuse astrocytoma—MYB altered." (PMID 35169893, 2022). "We found MYB- translocations with exon 2 or 3 of PCDHGA1 5/10 and 4/10 grade II gliomas respectively, and MYBL1 rearrangements in 6/9 of the samples examined." (PMID 35574540, 2022). "In the present study, we used multiple newly implemented techniques to investigate some of the genetic alterations in IDH1, IDH2, CDKN2A, MYB and MYBL1 in pediatric low-grade gliomas." (PMID 35574540, 2022). "The binding of transcription factors at the SMC4 promoter region is predicted and MYB and E2F1 are identified as potential transcription factors for SMC4 in glioma patients." (PMID 34868977, 2021).